SNORA8 (small nucleolar RNA, H/ACA box 8)
Synonyms: ACA8
Gene: Small nucleolar RNA gene on chromosome 11 (93,732,361 to 93,732,499, reverse strand). Ensembl gene ENSG00000207304.
Gene Ontology:
Biological process: RNA processing
Cellular component: nucleolus
Homologues: Orthologues: chimpanzee SNORA8 (100% identical), macaque SNORA8 (99% identical), rabbit SNORA8 (94% identical), pig SNORA8 (91% identical), dog SNORA8 (90% identical), mouse Gm25791 (90% identical), mouse Gm26236 (88% identical).
Diseases named in the same sentence as SNORA8 in open-access papers:
SNORA8 is named in the same sentence as 1 disease in open-access papers, as found by Europe PMC text mining. Sharing a sentence is not in itself a finding about the gene and the disease.
SNORA8 shares sentences with these, for which no sentence is quoted: infection (1 paper).